TNF (tumor necrosis factor)
Diseases named in the same sentence as TNF in open-access papers (continued):
Sharing a sentence is not in itself a finding about the gene and the disease.
cognitive decline (continued). "Findings indicated that higher serum IgG antibodies to periodontal pathogens and elevated inflammatory mediators, notably tumor necrosis factor-alpha (TNF‐α), correlated with greater cognitive decline and markers of AD neurodegeneration, including MRI outcomes and APOE ε4 status." (PMID 41890452, 2026). "Opioids may induce cognitive decline through neuroinflammation, increasing hippocampal inflammatory markers (IL-1β, IL-6, TNFα) observed in animal studies." (PMID 40657909, 2025). "Moreover, gingipain levels and antibodies against periodontal pathogens, including P. gingivalis, are proportionally related to TNF-α levels and cognitive decline." (PMID 40559320, 2025). "Therefore, TNFα and NF-kB were selected as markers of inflammation and investigated by mimicking the condition of cognitive decline in vitro by treatment with 200 μM H2O2." (PMID 40807615, 2025). "Additionally, certain inflammatory cytokines, such as tumor necrosis factor (TNF)-α, have been proposed to be associated with the clinical severity of CSVD, including cognitive decline." (PMID 41000387, 2025). "In addition, cytokines including IL-10, IL-6, and TNF regulate synaptic pruning, elimination, and plasticity; their imbalance may therefore cause excessive synapse loss or impaired circuit refinement, ultimately leading to cognitive decline or visual dysfunction." (PMID 41226665, 2025). "Research conducted by the world-renowned pediatric sleep expert Dr. David Gozal and others indicates that chronic fragmented sleep can lead to cognitive decline, increased expression of inflammatory markers such as NF-κB, TNF-α, and IL-1β, as well as heightened activation of microglia." (PMID 40893780, 2025). "Additionally, we studied the correlation between low TGF-β1 concentrations and elevated TNF-α plasma concentrations specifically in young adult DS individuals and the correlation between these cytokines and cognitive decline." (PMID 38576478, 2024). "Aβ1-40 induces the activation of several TNF-α-dependent intracellular signaling pathways that play a key role in controlling COX-2 upregulation and activation, synaptic loss, and cognitive decline in mice, which may ultimately lead to AD." (PMID 38988327, 2024). "To explore potential interactions between TGF-β1 and TNF-α in the early phase of cognitive decline in individuals with DS, we investigated the correlation between plasma concentrations of these two cytokines in both young and older adult DS individuals without AD." (PMID 38576478, 2024). "Furthermore, compared with low baseline TNFα levels, the higher baseline TNFα levels have presented a correlation with faster cognitive decline, suggesting that cytokines play an unneglectable part in AD clinical symptoms." (PMID 39500351, 2024). "Similarly, increased levels of TNF-α found in AD and PD affected patients’ cerebrospinal fluid and serum directly correlate with the diseases’ markers of severity, including cognitive decline." (PMID 39425138, 2024). "TNF-α has been found to accumulate within Aβ plaques in the postmortem brains of patients with AD and in the plasma and cerebrospinal fluid (CSF), thus triggering disease progression and accelerating cognitive decline." (PMID 38397814, 2024). "Further investigation into the underlying mechanisms revealed that the signaling of tumor necrosis factor-α (TNF-α) was downregulated in the hippocampus tissues of APP/PS1;SARM1Nestin-CKO mice, thereby alleviating the cognitive decline, Aβ deposition and inflammatory infiltration." (PMID 37307837, 2024). "Starting from the inverse relationship between TGF-β1 and TNF-α plasma concentrations, the ratio between these two cytokines was then analyzed to create a composite biomarker able to characterize a model fitting with the assessment of cognitive decline." (PMID 38576478, 2024).
cognitive decline (continued). "The cognitive decline studied in the mice model is exaggerated microglia-mediated inflammation along with amplified IL-1β, and TNF-α, CCL2 chemokine as well as prolonged TNF-α cytokine/chemokine expression, and a distinct reactive morphological profile of microglia." (PMID 37228857, 2023). "Several studies have also demonstrated an association between elevated levels of proinflammatory markers, including C-reactive protein, IL-6, and tumor necrosis factor-alpha (TNF-α), and cognitive decline as well as an increased risk of neurodegenerative disorders (e.g., AD and vascular dementia)." (PMID 38089627, 2023). "MCR participants had the highest TNF-α level (9.5 ± 2.6 pg./mL) compared with slow gait (8.5 ± 2.8 pg./mL), subjective cognitive decline (7.1 ± 1.4 pg./mL) and healthy (7.0 ± 1.7 pg./mL) groups and, conversely, the lowest progranulin/TNF-α and IL-10/TNF-α ratio." (PMID 37371414, 2023). "Serum levels of cytokines, such as IL-1β, TNF-α, and IL-10, were higher in PD patients than age-matched non-PD controls; higher TNF-α levels were associated with a faster rate of motor decline and higher IL-1β levels with a faster rate of cognitive decline." (PMID 36832181, 2023). "A 6-month study exploring the association between TNF-α levels and cognitive performance in 300 subjects with varying AD severity, found that acute inflammation correlated with a twofold cognitive decline increase, and high-baseline TNF-α levels quadrupled the decline." (PMID 38201258, 2023). "To test this hypothesis, we examined 915 individuals aged 45–74 years at baseline and evaluated whether higher levels of 3 circulating proinflammatory mediators, TNF-α, IL-6, and hs-CRP, could be associated with cognitive decline after 10 years." (PMID 36195448, 2022). "Perioperative neutralization of either HMGB1 tumor necrosis factor α (TNFα), IL-1β, or IL-6 can block the development of postoperative cognitive decline but may also interfere with healing." (PMID 36778590, 2022). "After Aβ production, microglia initiate an innate immune response that contributes to neuronal damage and cognitive decline, leading to sustained production and secretion of proinflammatory mediators, including interleukin (IL)-6, IL-1β, and tumor necrosis factor-α (TNF-α)." (PMID 36281465, 2022). "An increase in the serum levels of TNF-α resulted in a two-fold increase in the rate of cognitive decline over 6 months, and high baseline levels of TNF-α were associated with a four-fold increase in the rate of cognitive decline." (PMID 33716675, 2021). "It has been speculated that increased brain levels of TNF-α might be involved in cognitive decline in brain disorders via potentiation of glutamate excitotoxicity (reviewed in36)." (PMID 33980934, 2021). "Our finding that HD BPA increased neuroinflammatory TNFα expression, which has been shown to impair memory, suggests renal oxidative stress and H2S decline combined with brain inflammatory signaling contribute to cognitive decline." (PMID 34314248, 2021). "In fact, TNF-α may exert potent effects upon amyloidosis and neurodegeneration, along with learning and memory deficits in AD and, cognitive decline may be more rapid in patients with high levels of TNF-α." (PMID 35250531, 2021). "On the other hand, treatment with biological anti-tumor necrosis factor (TNF) therapies in RA patients may be protective, showing a lower risk percentage of developing cognitive decline." (PMID 33530359, 2021). "It has been well-established that tissue trauma released damage-associated cytokines, including TNF-α, could break the blood–brain barrier (BBB) and result in neuroinflammation and concomitant cognitive decline." (PMID 33708168, 2021). "Moreover, IL-1β, TNF-α production and an increase in the apoptosis can reduce adult hippocampal neurogenesis and produce the age-related cognitive decline." (PMID 32059688, 2020).
cognitive decline (continued). "The extent of the elevation of proinflammatory cytokines (IL-1β, IL-6, TNF-α, etc.)in both the central nervous system and the systemic circulation after surgery may relate to the degree of cognitive decline." (PMID 32214903, 2020). "High plasma TNF-α levels are predictive of muscle strength and cognitive declines." (PMID 32257550, 2020). "Finally, TNF-α significantly contributes to promote insulin resistance and the following cognitive decline in AD." (PMID 32296418, 2020). "In addition, soluble TNF-α has a saturable transport system at the BBB, and increased serum levels of TNF-α have been associated with increased rates of cognitive decline in AD patients." (PMID 33233734, 2020). "Functional inhibition of IL-1β could mitigate the neuroinflammation, and peripheral TNF-α blockade could reduce the release of IL-1β and prevent neuroinflammation and postoperative cognitive decline." (PMID 30501622, 2018). "While many systemic inflammatory molecules may exacerbate cognitive decline, the role of systemic TNF-α has been of particular interest." (PMID 27633985, 2017). "While many systemic inflammatory molecules may exacerbate cognitive decline, the role of systemic TNF-α is currently of particular interest." (PMID 27633985, 2017). "The current data imply that a modest level of TNFα modulation, using an orally bioavailable small molecule, is effective in preventing cognitive decline and reducing PHF tau and insoluble amyloid pathology while not impairing the central or peripheral immune system or inducing other adverse effects." (PMID 26436670, 2015). "Our data suggest that prolonged MV further aggravates cognitive decline after surgery that may stem from upregulation of hippocampal IL-1β, IL-6 and TNFα, partially via activation of gliocytes in surgical mice." (PMID 25887955, 2015). "Prolonged MV after surgery further aggravates cognitive decline that may stem from upregulation of hippocampal IL-1β, IL-6 and TNFα, partially via activation of gliocytes in the surgical mouse hippocampus." (PMID 25887955, 2015). "And the cognitive decline in patients can be improved by TNF-α inhibition." (PMID 25815030, 2015). "Peripheral blockade of TNF-α could limit the release of IL-1 and prevent neuro-inflammation and cognitive decline in a mouse model of surgery-induced cognitive decline." (PMID 24236147, 2013). "Terrando explained that TNF-α was important in cognitive decline." (PMID 24236147, 2013). "The present study suggests that TNF/TNFR1 signaling may also contribute to cognitive decline during aging through its effects on LTD mechanisms." (PMID 22666474, 2012). "In addition, the rate of cognitive decline was four fold increased in patients with high basal levels of TNF-alpha." (PMID 22191060, 2011). "Similarly, this study showed a notable decline in IL-6, IL-1β, and TNF-α levels upon OPB administration at both high and low doses, indicating the potential of OPB to mitigate neuroinflammation associated with learning ability and cognitive decline." (PMID 41557677, 2026). "The molecular mechanisms underlying the non-motor symptoms of PD remain unclear with neuroinflammation being linked to symptoms such as cognitive decline in PD, and elevated serum levels of IL-6 and TNFα/TNFα correlating with non-motor symptom severity." (PMID 40564225, 2025). "Elevated plasma levels of IL- 6, and TNF-α have been negatively correlated with motor and cognitive outcomes in PD, suggesting that systemic inflammation may exacerbate both motor dysfunction and cognitive decline." (PMID 40407975, 2025). "Thus, the multi-dimensional effect of NAT on markers like NFκB, CREB, Tau, SP, AChE, TNF-α, and IL-6 could suggest its ability to ameliorate the neuroinflammation-induced cognitive decline in AD." (PMID 38091207, 2024).
cognitive decline (continued). "This is supported by findings that reported the correlation between severe infections and accelerated cognitive decline in AD, linked to increased levels of peripheral tumor necrosis factor alpha (TNF-α) and the beneficial role of non-steroidal anti-inflammatory drugs in lowering the disease risk." (PMID 38674579, 2024). "Previous studies have shown that the TNF‐α levels in the peripheral blood of AD group were higher than in that of healthy control group, and that elevated levels of TNF‐α from the periphery, which are linked to systemic inflammation, are associated with cognitive decline in AD patients." (PMID 39236111, 2024). "In addition, TNF-α can modulate BBB permeability and promote Aβ peptide accumulation, and elevated plasma levels of this pro-inflammatory cytokine are associated with more severe cognitive decline." (PMID 36613538, 2022). "This study substantiates the key contribution of inflammatory markers (i.e., TNF-α) in combination with plasma Aβ1−42 levels and increased proNGF levels to better predict the worsening of “latent” AD pathology with the consequential cognitive decline in Down syndrome patients." (PMID 32296418, 2020). "Moreover, HMGB1 suppression could decrease proinflammatory cytokines (TNF-α, IL-1β, and IL-6), attenuate hippocampal atrophy, and improve cognitive decline." (PMID 32245271, 2020). "Emerging evidence highlights maladaptive microglial activation, chronic cytokine signaling (including IL-1β, TNF-α, and IL-6), and hypothalamic-pituitary-adrenal (HPA) axis hyperactivity as pivotal contributors to neuronal damage and cognitive decline." (PMID 41907842, 2026). "We investigated the relationship between baseline circulating levels of inflammatory (TNF-α, IL-1ß) and endothelial cell markers (VCAM-1, ICAM-1, E-selectin) and 18-month cognitive decline (ADAS-cog12) in 266 mild-to-moderate AD patients from the NILVAD study." (PMID 39085534, 2025). "Among these markers are Interleukin-1α (IL-1α), Interleukin-1β (IL-1β), Interleukin-6 (IL-6), tumor necrosis factor-α (TNFα), and CCL2, contributing to microglial activation, synaptic irregularities, cognitive decline, and hindered adult neurogenesis." (PMID 40703771, 2025). "The best cutoff values for serum α-klotho, FGF-23, IL-6, TNF-α, BDNF, BMI, and calcium levels for the diagnosis of dialysis-induced cognitive decline were 469.5 pg/mL, 1,264.5 ng/mL, 1.8 pg/mL, 21.1 pg/mL, 20.0 ng/mL, 23.9 kg/m2, and 2.52 mmol/L, respectively." (PMID 40950978, 2025). "This process enhances the production of inflammatory mediators such as IL-1β, IL-6, IFN-γ, TNF-α, CCL2, GMF, NO, and ROS, ultimately driving inflammatory responses and cognitive decline in neurodegenerative diseases." (PMID 40556958, 2025). "Analysis of all dialysis-induced cognitive decline cases revealed that the area under the ROC curve for α-klotho, FGF-23, IL-6, TNF-α, BDNF, BMI, and calcium were 0.58, 0.55, 0.58, 0.59, 0.70, 0.64, and 0.62, respectively." (PMID 40950978, 2025). "Inhibition of NF‐κB can reduce the expression of pro‐inflammatory cytokines (such as IL‐6, IL‐1β, and TNF‐α) and increase the expression of BDNF, thereby ameliorating the cognitive decline of diabetic mice." (PMID 37864452, 2024). "Taken together, these results suggested that SARM1 deletion in CNS alleviated cognitive decline, Aβ deposition and inflammatory infiltration in APP/PS1 mice by downregulation of TNF-α signaling." (PMID 37307837, 2024). "In line with these previous studies, the results showed that the levels of IL‐1β, IL‐6, and TNF‐α were increased in the hippocampus of the mice exposed to CSD, which contributed to the observed cognitive decline." (PMID 38688894, 2024). "Six genes were associated with frailty and cognitive decline in Sargent’s recent review: IL-6 rs1800796, TNF rs1800629, IL-18 rs360722, IL1-beta rs16944, and COMT rs4680 for cognitive decline and COMT rs4646316 for frailty." (PMID 32257550, 2020).
cognitive decline (continued). "The proinflammatory cytokines, such as interleukin 1β (IL-1β) and tumor necrosis factor α (TNF-α), have been reported to play an important role in mediating surgery-induced systemic and central inflammation, ultimately resulting in cognitive decline." (PMID 29249869, 2017). "In addition, increased levels of inflammatory markers like IL-1β, IL-12, TNF-α, CRP, low CSF and serum BDNF, and altered adipokines are observed in individuals exhibiting both cognitive decline and depressive symptoms." (PMID 40807098, 2025). "Increased cytokine activity (IL-6, TNF-α, IFN-γ) and T-cell infiltration may affect brain function, leading to cognitive decline." (PMID 40124366, 2025). "In the WHI cohort, higher DII scores were associated with elevated concentrations of inflammatory markers, including IL-6, TNF-α, and hs-CRP, which can cross the blood–brain barrier, induce neuroinflammation, and damage neurons and synaptic function, ultimately leading to cognitive decline." (PMID 41228485, 2025). "Nonetheless, in our study, diagnostic accuracy of α-klotho, IL-6, TNF-α, and BDNF is low, and there is no statistical difference between the cognitive decline and cognitive undiminished groups." (PMID 40950978, 2025). "TNF-α is colocalized with Aβ plaques in AD human brains and animal models, and TNF-α mediated inflammation contributes to Aβ plaques and tau hyperphosphorylation, which result in neuronal damage and cognitive decline." (PMID 38500108, 2024). "The literature has shown that chemotherapy directly results in an upregulation of various well-known pro-inflammatory mediators, such as IL-1β, TNF-α, MCP-1, IL-6, etc., which contribute to symptoms including but not limited to fatigue, peripheral neuropathy, and cognitive decline." (PMID 38731449, 2024). "Baseline TNF-α did not predict cognitive decline, and hs-CRP did not predict cognitive performance or decline after 10-years." (PMID 36195448, 2022). "We hypothesized that low-grade inflammation, estimated by interleukin-6 (IL-6), tumor necrosis factor alpha (TNF-α), and high-sensitivity CRP (hs-CRP), is a predictor of cognitive decline in the general population." (PMID 36195448, 2022). "Upon interaction with Aβ, activated microglia initiate an innate immune response that leads to sustained production and secretion of pro-inflammatory mediators including interleukin (IL)-6, IL-1β, and tumor necrosis factor-α (TNF-α), contributing to neuronal damage and cognitive decline." (PMID 35264247, 2022). "Additionally, it would be interesting if patients with cognitive decline improve in the follow-up and are related to improvement in RPC values or the use of anti-TNF." (PMID 35885032, 2022). "Elevated TNF-α crosses the BBB leading to microglial activation, increased ROS and further TNF-α release in the brain, leading to mitochondrial dysfunction and subsequent cognitive decline." (PMID 30100992, 2018). "Importantly, in an animal model of AD, TNF mediates, likely via TNFR1, the Aβ-induced activation of COX-2, which is correlated to the cognitive decline of the animals." (PMID 25834699, 2015). "Our study's findings contribute to the existing literature by suggesting that inflammatory markers (TNF-α and IL-1ß) and endothelial cell markers (E-selectin, ICAM-1, and VCAM-1) have neither cross-sectional nor longitudinal associations with cognitive decline in AD patients." (PMID 39085534, 2025). "In addition, recent meta-analyses found relationships between higher baseline IL-6 but not TNFα and steeper cognitive decline, with less published research on IL-1β levels and longitudinal cognitive change." (PMID 39055623, 2024). "These inconsistencies maybe due to the fact that the relationship between CSF TNFα levels and cognitive decline is actually non-linear." (PMID 36288380, 2022).